TNF (tumor necrosis factor)
Diseases named in the same sentence as TNF in open-access papers (continued):
Sharing a sentence is not in itself a finding about the gene and the disease.
ankylosing spondylitis (continued). "Tumor necrosis factor (TNF) antagonists reduce the signs and symptoms of spondyloarthritides, including ankylosing spondylitis (AS) and psoriatic arthritis (PsA)." (PMID 20553600, 2010). "Based on the activity of the ankylosing spondylarthritis a TNF-blockade with etanercept (50 mg/week s.c.)was initiated." (PMID 19232095, 2009). "Of the nine patients with ankylosing spondylitis, one was on TNFα antagonist therapy and had a right orbital apex localization of aspergillosis." (PMID 19886992, 2009). "An additional analysis showed that 28 patients with various non-RA rheumatic diseases, including 12 juvenile idiopathic arthritis, 6 psoriatic arthritis, and 3 ankylosing spondylitis, had been treated with TNF-α-blocking therapy in the study centre." (PMID 15899052, 2005). "Morphea is a localized autoimmune fibrosing disorder that may paradoxically develop during anti-TNFα agents in ankylosing spondylitis (AS)." (PMID 42040377, 2026). "Similarly, men with ankylosing spondylitis showed greater improvement in disease activity scores than women after 12 weeks of anti-TNF therapy." (PMID 40741215, 2025). "Furthermore, other anti-TNF agents, aside from the three agents under our investigation, demonstrated efficacy in reducing the occurrence of uveitis in patients with ankylosing spondylitis." (PMID 38337605, 2024). "Moreover, the potential extensibility of our findings to other rheumatic diseases treatable with TNF-α inhibitors, such as ankylosing spondylitis and psoriatic arthritis, is promising." (PMID 39064094, 2024). "However, tumor necrosis factor alpha inhibitor treatment significantly increased the incidence of overall adverse events, nasopharyngitis, headache, and injection-site reactions in ankylosing spondylitis patients when compared with placebo." (PMID 36865909, 2023). "The ReMonit study is a 3-armed, single-site, randomized, controlled, open-label noninferiority trial including patients with axial spondyloarthritis with low disease activity (Ankylosing Spondylitis Disease Activity Score <2.1) and on stable treatment with a tumor necrosis factor inhibitor." (PMID 38150310, 2023). "Moreover, Liu and colleagues observed greater efficacy of TNF-α inhibitors than the placebo in patients with ankylosing spondylitis." (PMID 36836166, 2023). "These negative results are in line with a similar study describing the effects of the anti-TNF treatment in patients with RA and ankylosing spondylitis; however, there are also studies that describe the decline of LDL concentrations after the treatment application." (PMID 37987275, 2023). "Furthermore, the administration of Anti-TNFα treatment was found to reduce the elevated levels of serum Indian Hedgehog in individuals with ankylosing spondylitis and impact the expression of Hedgehog pathway target genes with functional significance." (PMID 37608254, 2023). "This study aimed to investigate the effectiveness of a supervised group exercise therapy based on the biopsychosocial model introduced simultaneously with antitumor necrosis factor (TNF) therapy in anti-TNF-naive patients with active ankylosing spondylitis (AS)." (PMID 36326328, 2022). "Etanercept, a TNF-α inhibitor, is one of the few treatment options for ankylosing spondylitis." (PMID 33628645, 2021). "Furthermore miR-130a is downregulated in the PBMC of patients with ankylosing spondylitis and in vitro studies showed that inhibition of miR-130a increases TNF-α expression, while increased miR-130a inhibits apoptosis and promotes proliferation of T cells." (PMID 33746971, 2021). "Indeed, data from the BSR Biologics Register for Ankylosing Spondylitis indicate that in a real-world patient population around half of patients respond to TNF inhibition, compared to > 60% in the clinical trials that led to the licensing of these agents." (PMID 33993880, 2021).
ankylosing spondylitis (continued). "In the BIOBADASER registry, among 4706 patients with chronic arthritis—including RA, PsA, and ankylosing spondylitis (AS)—10% had been treated with more than one anti-TNFα over a 4-year period; 88% of PsA patients continued with their first anti-TNFα drug for 12 months vs. 83% of RA patients." (PMID 34136971, 2021). "However, this study assessed the population of patients with ankylosing spondylitis (47 patients), paying attention to the importance of treatment with a tumor necrosis factor (anti-TNF) inhibitor (23 patients)." (PMID 33419108, 2021). "In addition, serum levels of sTim-4 were significantly increased in ankylosing spondylitis patients, which was positively correlated with TNF-α levels and Bath ankylosing spondylitis disease activity index." (PMID 32300343, 2020). "Remarkably, TNF inhibitor-naïve patients had better treatment outcomes concerning Assessment of SpondyloArthritis International Society 20/40 response, partial remission, and Bath Ankylosing Spondylitis Disease Activity Index 20/50." (PMID 31555262, 2019). "From PSARA, a prospective observational study, we examined 51 SpA patients (31 psoriatic arthritis (PsA), and 20 ankylosing spondylitis (AS)), starting tumor necrosis factor (TNF) inhibitor alone (n = 25), combined with methotrexate (MTX) (n = 10), or MTX monotherapy (n = 16)." (PMID 31335881, 2019). "Meanwhile, it seems that TNF inhibitors in ankylosing spondylitis may present a better safety profile than we thought." (PMID 31172410, 2019). "Recent data suggest that anti-TNF doses can be reduced in ankylosing spondylitis (AS) patients." (PMID 30953541, 2019). "In our cases series, a patient treated with JAK2 inhibitor, indeed, developed MZL; however, it should be noted that this patient's exposure to anti-TNF (tumor necrosis factor) agents for her ankylosing spondylitis could have also contributed to her lymphoma." (PMID 31781224, 2019). "The effects of neridronate (an intravenous N-bisphosphonate with high skeletal affinity) have been investigated in terms of disease activity in an open-label study vs infliximab (a TNF inhibitor approved for the treatment of SpA) in patients affected by ankylosing spondylitis (AS)." (PMID 31766755, 2019). "Since vaspin also exerts anti-inflammatory properties, like the suppression of TNF-alpha, it would be conceivable that lower vaspin levels might be a consequence of the increase of pro-inflammatory cytokines in ankylosing spondylitis." (PMID 27383120, 2016). "Men had a higher prevalence of ankylosing spondylitis (0.23% versus 0.14%, P < 0.001), a higher frequency of anterior uveitis (25.5% versus 20.0%, P < 0.001) and were more likely to receive tumor necrosis factor inhibitors than women (15.6% versus 11.8% in 2009, P < 0.001)." (PMID 25956915, 2015). "Data from a non-randomized case–control study in patients with inflammatory arthritis (RA, PsA and ankylosing spondylitis) showed that long-term use of anti-TNF-α therapy may result in a significant improvement in PWV compared to the non-treated group." (PMID 25890227, 2015). "Recently, anti-TNF therapy was shown to downregulate IL-17 expression and the frequency of Th17 cells in ankylosing spondylitis patients; therefore, we tested whether it was also the case in chronic T. cruzi infection." (PMID 25140115, 2014). "On the other hand, a recent study showed a negative correlation between ADMA levels and total cholesterol and LDL-C in a series of patients with ankylosing spondylitis undergoing period anti-TNF-alpha-monoclonal antibody therapy that at the time of the study had low disease activity." (PMID 24864133, 2014). "Simon and Burgor-Vargas described a patient with ankylosing spondylitis (AS) and vitiligo who was treated with infliximab (a chimeric monoclonal anti-TNF antibody), which resulted in gradual fading of vitiligo lesions suggesting that TNF-α was involved in the pathogenesis of vitiligo." (PMID 23284977, 2012).
ankylosing spondylitis (continued). "Similarly, Antitumor necrosis factor (TNF) α therapy has now been used in the treatment of patients with ankylosing spondylitis with good success in terms of improving functionality, pain scores, and sleep disturbance." (PMID 21547038, 2011). "In addition, TNF-α blockers have been shown to be very effective and safe for the treatment of a variety of sequela secondary to systemic diseases, such as RA, PsA, ankylosing spondylitis, juvenile idiopathic arthritis (JIA), and Crohn’s disease." (PMID 21180427, 2010). "As TNFα blockade is known to be an exceedingly effective therapeutic approach in many patients with ankylosing spondylitis, the effects of apremilast in ankylosing spondylitis are currently being tested in a phase II, randomised, double-blinded, clinical control study at our centre." (PMID 20525198, 2010). "Furthermore, we describe one patient in whom TNF-blockade was initiated due to an ankylosing spondylarthritis." (PMID 19232095, 2009). "Recent data about radiographic progression during treatment with tumor necrosis factor-alpha (TNF-α) blocker agents in patients with ankylosing spondylitis (AS) have prompted an intensive discussion about the link between inflammation/bone destruction and new bone formation and the order of events." (PMID 18945353, 2008). "For example, the higher LTBI detection rates in ankylosing spondylitis patients may reflect the immunological nature of the disease, or a greater likelihood of initiating TNF-α blockers rather than a true predisposition." (PMID 40711067, 2025). "A search was performed in the PubMed database using the following keywords: ("TNF alpha inhibitors" OR "anti TNF-a" OR "TNF-a inhibitors" OR "anti TNF-alpha" OR "Etanercept " OR "Golimumab" OR "Infliximab" OR "Certolizumab pegol" OR "Adalimumab") AND "ankylosing spondylitis"." (PMID 38952586, 2024). "Similarly, plasma sTIMD4 levels in patients with ankylosing spondylitis were significantly higher than those in the control group, and positively correlated with plasma tumor necrosis factor‐α (TNF‐α) levels and Barth disease activity index of ankylosing spondylitis." (PMID 37426678, 2023). "The decrease in ferroptosis and lipid ROS levels induced by TNF could be eliminated by adalimumab, a fully human monoclonal TNF antibody that has been approved for the treatment of RA, juvenile idiopathic arthritis, ankylosing spondylitis, and inflammatory bowel disease." (PMID 35115492, 2022). "It has even been documented that MIF induces TNF production in monocytes, activates β-catenin in osteoblasts and promotes the mineralization of osteoblasts, indicating that the MIF/CD74 axis is linked to inflammation and new bone formation seen in ankylosing spondylitis." (PMID 34621738, 2021). "Hence, we investigated, through a case-control study, whether single-nucleotide polymorphisms of TNF and IL17 genes are associated with SpA, ankylosing spondylitis (AS), and psoriatic arthritis (PsA) in a mixed Brazilian population." (PMID 29849482, 2018). "From these findings, the combined blocking of TNF-α and IL-17A may represent a new option for controlling inflammatory bone disorders as in RA, psoriatic arthritis as well as in ankylosing spondylitis and inflammatory subsets of OA and even common osteoporosis." (PMID 25904914, 2015). "Tumor necrosis factor-alpha (TNF-α) inhibitors, such as adalimumab, are integral in the managing refractory ankylosing spondylitis (AS)." (PMID 41626126, 2026). "TNF inhibitors (TNFi) and JAK inhibitors (JAKi) have both demonstrated efficacy in ankylosing spondylitis (AS) through randomized controlled trials (RCTs) and real-world data." (PMID 40936891, 2025). "This study evaluated a synthetic KYNA analog’s effects on TNF-α, S100A8/9, S100A12, α-defensin, and interleukin-17 (IL-17) production and TSG-6 expression in ankylosing spondylitis (AS) and psoriatic arthritis (PsA)." (PMID 41465233, 2025).
ankylosing spondylitis (continued). "In contrast, our patients with ankylosing spondylitis had been treated with cs-DMARDS (87.9%) and/or anti-TNF agents (32.8%) for at least three months." (PMID 40564778, 2025). "It has been shown that tumor necrosis factor (TNF)-α, interleukin (IL)-1β are significantly increased in patients with OA, RA, ankylosing spondylitis, and psoriatic arthritis." (PMID 39022340, 2024). "In an ankylosing spondylitis mouse model, IAA reduced inflammation by suppressing TNF-α, IL-6, IL-17A, and IL-23, while enhancing the expression of IL-10." (PMID 39759289, 2024). "With a Bath Ankylosing Spondylitis Disease Activity Index (BASDAI) score of 8, the decision was made to start anti-TNF-α therapy for better disease management." (PMID 39493161, 2024). "A correlation between circulating TNF-α levels and ETN clearance has recently been evaluated in healthy volunteers and in subjects with ankylosing spondylarthritis." (PMID 35887671, 2022). "Based upon the observations in cultured cells, rodents, and patients with ankylosing spondylitis of reduced inflammation after exposure to heat stress, we further hypothesized that leg HT would reduce the plasma levels of interleukin 6 (IL‐6) and tumor necrosis factor alpha (TNF alpha)." (PMID 33369253, 2021). "Long-term treatment with TNF inhibitors even increases the rate of fracture, although BMD is increased in patients with ankylosing spondylitis." (PMID 35011694, 2021). "Among the treatment for ankylosing spondylitis (AS) currently available, there are several TNF-α inhibitors, targeting the proinflammatory cytokine TNF-α, released by a variety of cell types including NK cells." (PMID 33679757, 2021). "Since these publications, the intravenous (IV) formulation of the TNF inhibitor golimumab (GOL IV) was approved by the US Food and Drug Administration (FDA) for the treatment of adults with active ankylosing spondylitis." (PMID 32107666, 2020). "Treatment efficacy was evaluated by use of the Bath Ankylosing Spondylitis Activity Index (BASDAI) score, and serum TNF-α and IL-6 levels were measured pre and post-treatment." (PMID 26245191, 2015). "Currently, subjective measures of disease activity, such as the Bath Ankylosing Spondylitis Disease Activity Index (BASDAI) or the global opinion of the physician, are most important in the evaluation of TNF-α blocking therapy in AS." (PMID 22546520, 2012). "Randomized controlled trials (RCTs) have demonstrated that the tumor necrosis factor alpha (TNF-α) blocking agents infliximab, etanercept, and adalimumab are effective in the treatment of Ankylosing Spondylitis (AS)." (PMID 21689401, 2011). "As expected, HLA-B27 was significantly higher in both anti-TNF groups, with and without TB, due to presence of patients with ankylosing spondylitis in those groups." (PMID 40307303, 2025). "HLA-B27 was significantly higher in both anti-TNF groups, with and without TB, due to presence of patients with ankylosing spondylitis in those groups." (PMID 40307303, 2025). "Tumor necrosis factor (TNF) blockers, comprising etanercept, infliximab, adalimumab, certolizumab pegol, and golimumab, have been well-recognized as one of the most promising therapies for various inflammatory diseases, including ankylosing spondylitis." (PMID 39963435, 2025). "In ankylosing spondylitis, PET/CT was used to evaluate treatment response to anti-TNF treatment." (PMID 39729191, 2025). "A cohort study based on the population in Brazil disclosed that 78% of patients with ankylosing spondylitis (AS) initiated anti-TNF drug treatment at no charge, with a median monthly per capita cost of $1650." (PMID 38415452, 2024). "Again, in a study evaluating the efficacy of TNF inhibitor in the obese group among patients with ankylosing spondylitis, RA and psoriatic arthritis patients, a negative correlation was found between the BMI and response to anti-TNF treatments." (PMID 38813042, 2023).
ankylosing spondylitis (continued). "This study concluded that ankylosing spondylitis does not have a significant relationship with severe infections, especially when considering the use of TNF blockers." (PMID 38053214, 2023). "Ankylosing spondylitis (AS) is a condition that is treated with nonsteroidal anti‐inflammatory drugs and biological drugs such as anti tumor necrosis factor alpha (TNF‐α)." (PMID 37382255, 2023). "Recent literature involves many cases with lymphoma and ankylosing spondylitis (AS) with or without the use of TNF inhibitors." (PMID 36128217, 2022). "Tumor necrosis factor inhibitors (TNFis) have revolutionized the management of ankylosing spondylitis (AS); however, the lack of notable clinical responses in approximately one-half of patients suggests important heterogeneity in treatment response." (PMID 35289857, 2022). "In patients with ankylosing spondylitis in clinical remission for at least 6 months, dose reduction is non-inferior to full TNF inhibitor doses to maintain LDA after 1 year." (PMID 30621746, 2019). "Tumor necrosis factor (TNF) blockers have a high efficacy in treating Ankylosing Spondylitis (AS), yet up to 40% of AS patients show poor or even no response to this treatment." (PMID 31195969, 2019). "Increased expression of A2AR and A3R adenosine receptors has been measured in white cells of RA and in ankylosing spondylitis patients, an effect that decreased after anti TNF-alpha treatment, consistent with the known effect of TNF-alpha on the expression of adenosine A2AR via NF-kB activation." (PMID 32038258, 2019). "UC/IBDU patients with sacroiliitis/ankylosing spondylitis received more frequently vitamin B12 supplementation and anti-TNF antibodies when compared to UC/IBDU patients without sacroiliitis/ankylosing spondylitis." (PMID 31039159, 2019). "Currently, the decision to introduce anti-TNFα treatment is evaluated based on high disease activity, in clinical practice usually assessed using the Bath Ankylosing Spondylitis Disease Activity Index (BASDAI), and a lack of improvement in previous treatment." (PMID 29546695, 2018). "Accordingly, data on AS disease activity at the close time after TNF suspension were to track patient’s perspectives and classified with applying neither Bath Ankylosing Spondylitis Disease Activity Index nor Ankylosing Spondylitis Disease Activity Score." (PMID 27101309, 2016). "Demographic and disease characteristics at baseline showed significantly more active disease (Bath Ankylosing Spondylitis Disease Activity Index, total back pain, nocturnal back pain, patient global, ASDAS, CRP) (P <0.0001 for all variables) in patients who received TNFα inhibitor therapy." (PMID 24755322, 2014). "In another series of non-diabetic and mostly non-obese patients with ankylosing spondylitis undergoing anti-TNF-α therapy, adiponectin concentrations related to insulin sensitivity and marginally to low BMI." (PMID 24286214, 2013). "Sclerostin levels have been reported to be low in ankylosing spondylitis (AS), but there is no data regarding the possible role of this Wnt inhibitor during anti-tumor necrosis factor (TNF) therapy." (PMID 23062122, 2012). "Economic assessments conducted in the UK further support the cost-effectiveness of adalimumab and other anti-TNF agents compared with conventional therapy for treating patients with ankylosing spondylitis (AS) and non-radiographic axial spondyloarthritis (SpA)." (PMID 38415452, 2024). "For ankylosing spondylitis, MSC treatment for 6 months may increase the total effective rate; reduce erythrocyte sedimentation rate, intercellular adhesion molecules, and serum TNF-α; and improve pain and activity." (PMID 35371265, 2022). "While they did not reveal more CD-related complications, such as fistulas, abscesses or stenosis, or surgeries, they more frequently received vitamin B12 supplementation, mesalazin (5-ASA) and anti-TNF antibodies when compared to CD patients without sacroiliitis/ankylosing spondylitis." (PMID 31039159, 2019).